CD4 (CD4 molecule)
Diseases named in the same sentence as CD4 in open-access papers (continued):
Sharing a sentence is not in itself a finding about the gene and the disease.
HIV-1 infection (continued). "Of note, the decrease in the absolute number of CD31-CD4+ naïve T-cells associated with HIV-1 infection was greater than the decrease observed for any other CD4+ T-cell phenotype tested." (PMID 21298072, 2011). "Stable re-expression of a LEDGF/p75 ΔPWWP mutant in human LEDGF/p75-deficient CD4+ cells was reported to rescue HIV-1 infection exhibiting approximately 50% of the HIV-1 cofactor activity of LEDGF/p75 WT." (PMID 21510906, 2011). "HIV-1 infection was associated with significant telomere shortening within both subsets of naïve CD4+ T-cells across both age groups (younger: p = 0.0004 for CD31+, p = 0.0096 for CD31-; older: p<0.0002 for both naive subsets)." (PMID 21298072, 2011). "Compounding this cell loss is the additive effect of aging and HIV-1 infection on telomere shortening within both subsets of naïve CD4+ T-cells." (PMID 21298072, 2011). "We recently showed that Vif also causes CD4+ T-cell death and G2 arrest during HIV-1 infection, unveiling a connection between virus-induced cell cycle arrest and cytopathicity." (PMID 21569376, 2011). "In summary, we found that group B KIR haplotypes and lack ofspecific inhibitory KIR ligand genes, genotypes considered to favor NK cellactivation, are associated with CD4+ T cell loss during HIV-1 infection." (PMID 21347267, 2011). "Both older age and HIV-1 infection were associated with significantly decreased numbers of CD31+CD4+ T-cells." (PMID 21298072, 2011). "HIV-1 infection of the thymus contributes to the defective regeneration and loss of CD4+ T cells in HIV-1-infected individuals." (PMID 21639903, 2011). "The target cells expressing higher level of cathepsin B activity were less susceptible to the CD4-independent mNDK vector infection, suggesting that cathepsin B inhibits the CD4-independent HIV-1 infection." (PMID 21541353, 2011). "The viremic mice also showed CD4 T cell loss which is a characteristic feature of HIV-1 infection in the human." (PMID 21695116, 2011). "In particular, D2 BP provided the 2G12 dimer at 5–25 μg/ml, which was sufficient to prevent peripheral blood CD4 T cell loss and suppress the increase of the viral load following HIV-1 infection." (PMID 21187894, 2010). "In multivariate analyses, significant risk factors for clinical deterioration were HIV-1 infection and a low CD4+ count at tuberculosis diagnosis." (PMID 20353569, 2010). "In multivariate analysis, HIV-1 infection and a low CD4+ count at tuberculosis diagnosis were significant risk factors for clinical deterioration and death." (PMID 20353569, 2010). "We further evaluated the mice for evidence of helper CD4 T cell loss which is a characteristic hallmark of HIV-1 infection." (PMID 21203568, 2010). "Our results showed that passively transferred, purified 2G12 dimer is more potent than 2G12 monomer at preventing CD4 T cell loss and suppressing the increase of viral load following HIV-1 infection of humanized mice." (PMID 21187894, 2010). "It is now well established that HIV-1 infection causes a slow but progressive impairment of the immune system, which is accompanied by a chronic hyperactivation of CD4+ and CD8+ T cells." (PMID 21085612, 2010). "HIV-1 infection and a low CD4+ count were the only significant risk factors for clinical deterioration in multivariate analysis." (PMID 20353569, 2010). "Despite a few studies on the most acute stages of HIV-1 infection in humans, it is likely that there is a similar large and rapid loss of intestinal CD4+ T cells during the early periods of infection." (PMID 20485497, 2010). "Since CD4 T cell loss is a main characteristic of HIV-1 infection in humanized mice akin to that seen in the human, we further evaluated the virus challenged mice for any evidence of such loss." (PMID 21203568, 2010). "Early HIV-1 specific CD4+ T cell responses were associated with slower progression in HIV-1 infection." (PMID 20552033, 2010).
HIV-1 infection (continued). "As HIV-1 infection and malaria both influence CD4 count, difficulties arise when assessing associations between those infections and cellular immunity." (PMID 19922664, 2009). "After adjustment for CD4 count and age, low responders remained associated with HIV-1 infection (adjusted odds ratio (AOR):2.40; P = 0.01), parasite load (AOR:1.62; P = 0.06) and had less anemia (AOR:0.55; P = 0.07)." (PMID 19922664, 2009). "The host's genetic background plays a vital role in the evolution and immune control of HIV-1 infection and expression of particular HLA B alleles has been reported to have the strongest influence on viral load, CD4 count and selection pressure on the virus." (PMID 19142234, 2009). "In Luanshya, Zambia, an area where malaria is mesoendemic, HIV-1 infection is an important risk factor for severe malaria in adults, primarily in those with a low CD4 count." (PMID 19402961, 2009). "Although the depletion of gut-associated CD4+ T lymphocytes in early HIV-1 infection is well known, these new results demonstrate the effects of early HIV-1 infection on gut-associated and circulating B lymphocytes." (PMID 19582166, 2009). "In light of the evidence that suggests miRNAs play a role in the resistance of monocytes to HIV-1 infection, it is of interest that a number of host miRNAs have been implicated in causing latency in resting primary CD4+ T cells." (PMID 19486514, 2009). "Gag and Nef, were also found to be the most frequently targeted proteins by CD4+ T cells in clade B HIV-1 infection and in the less pathogenic HIV-2 infection." (PMID 19352428, 2009). "A low, moderate and high CCL3L1-CCR5 GRG status was associated with a step-wise increase in susceptibility to depletion of CD4+ T cells during HIV-1 infection, as well as impaired CD4+ T cell recovery during HAART." (PMID 18776933, 2008). "The reported low levels of CD4 and chemokine co-receptors CXCR4 and CCR5 on DCs are probably responsible for their weaker susceptibility to productive HIV-1 infection in vitro as compared to CD4+ T cells." (PMID 18373845, 2008). "Next, to examine the possibility that FPRL1 is involved in HIV-1 infection in vivo, we examined the susceptibility of NP-2/CD4/FPRL1 cells to primary HIV-1 isolates." (PMID 18577234, 2008). "HIV-1 infection induces aberrant immune activation of latently infected CD4+ T cells associated with an enhancement of expression of certain host genes despite the absence of expression of classical cell-surface activation markers." (PMID 17727722, 2007). "We have previously reported that CD4 T cells from some Vietnamese individuals who remain free of infection after several years of intravenous drug use show reduced susceptibility to HIV-1 infection." (PMID 17092330, 2006). "HIV-1 infection is associated with CD4+ T cell loss and progressive immune dysfunction, leading to impaired HIV-1 responses early after infection." (PMID 17183635, 2006). "From the studies conducted, we found lower levels of CD4 T cell activation and reduced in vitro susceptibility to HIV-1 infection in exposed seronegative individuals than in low-risk Central African blood donors." (PMID 16792805, 2006). "Activated CD4+ cells are highly susceptible to HIV-1 infection and typically die quickly as a result of the cytopathic effects either of the virus or of the host immune response." (PMID 16412247, 2006). "Since the discovery of HIV, many researchers were certain that CD4+ T cells were the only cells susceptible to HIV-1 infection." (PMID 17010197, 2006). "With this equipment available in the country we evaluated the CD4/CD8 ratio as an alternative diagnostic test for infant HIV-1 infection." (PMID 15683549, 2005). "Here, we show that IM28 can also prevent and inhibit the fusion of infected cells (TF228.1.16 cells) to naïve cells including 293/CD4+ cells, which are stably transfected with human CD4 and highly susceptible to HIV-1 infection, and SupT1 cells." (PMID 15707492, 2005).
HIV-1 infection (continued). "Furthermore, HIV-1 infection causes telomere attrition in host chromosomes, a critical factor contributing to CD4+ T cell senescence and apoptosis." (PMID 40244051, 2025). "Similarly, multiple studies have achieved successful CXCR4 gene disruption using CRISPR/Cas9, which conferred resistance to HIV-1 infection in both human and rhesus macaque CD4+ T cells and was associated with reduced viral p24 antigen production." (PMID 40699766, 2025). "VLA-4 is an adhesion molecule that is involved in trafficking of immune cells to inflammatory sites and has recently been shown to increase the susceptibility of resting CD4 + cells to HIV-1 infection after in vitro coculture with endothelial cells that express VCAM-1, the ligand for VLA-4." (PMID 39903363, 2025). "For example, the CM CD4+ T cells, which are at resting state in vivo, may become more susceptible to HIV-1 infection after in vitro stimulation." (PMID 41244297, 2025). "Additional investigation indicated that miR-21, one of these microRNAs, was decreased in monocytes during HIV-1 infection and was in charge of the rise in IP-10 levels that caused inflammation and the quick loss of CD4+ T cells, which is strongly associated with disease development." (PMID 40296890, 2025). "Whether this process occurs in vivo in PWH, and whether CD4 + T cells that receive CD32-containing membrane patches from other cell types via this mechanism are indeed more susceptible to HIV-1 infection, remains to be determined." (PMID 39903363, 2025). "Upon prolonged HIV-1 infection, there is a drastic depletion of infected and activated CD4+ T cells, which leads to the loss of cell-mediated immunity, rendering people living with HIV-1 (PLWH) susceptible to fatal opportunistic infections that are defined as AIDS." (PMID 40130873, 2025). "Furthermore, in HIV-1 infection, the replicative pressure to replace dead CD4+ T cells causes progressive telomere shortening (a phenomenon defined as telomere attrition), which is a hallmark of cellular senescence." (PMID 40244051, 2025). "Importantly, macrophage-derived membrane patches transferred to resting CD4 + T cells rendered these cells susceptible to HIV-1 infection by serving as hotspots for virus binding." (PMID 39903363, 2025). "HIV-1 infection increases TB risk through several mechanisms, including immune hyperactivation, exhaustion of the immune system, systemic inflammation, and depletion of CD4+ T cells, leading to a loss of TB control." (PMID 39181733, 2024). "To test this hypothesis, we first measured the expression of CCR5 and other select surface markers of CD4+ T cell HIV-1 infection susceptibility on cells isolated from the FRT." (PMID 39872519, 2024). "Because E2 is known to reduce CD4+ T cell HIV-1 infection susceptibility in vitro, we next assessed whether E2 treatment could reverse the observed increases in endometrial CD4+ T cell infection susceptibility following menopause as described in the methods." (PMID 39872519, 2024). "However, in some cases, such as HIV-1 infection, the virus induces necroptosis in infected CD4+ T lymphocytes and CD4+ T-cell lines, resulting in the progressive loss of CD4+ T cells." (PMID 38195700, 2024). "Thus, by the mid-1990s, papers in the JCI had established or confirmed that the major targets of HIV-1 were CD4+ T cells and monocytes, and that HIV-1 infection was indeed associated with cellular functional deficiencies, particularly in helper CD4+ T cells." (PMID 38949029, 2024). "Our findings show that a specific subset of Vδ1 T cells upregulates CD4 following activation and may represent a distinct population that become susceptible to HIV-1 infection in vivo." (PMID 39149467, 2024). "Previous work by our group has suggested that CD4+ T cell HIV-1 infection susceptibility may be greater in the ECX relative to the EM." (PMID 39872519, 2024).
HIV-1 infection (continued). "Overall, HIV-1 infection may increase the risk of TB through several mechanisms, independently of immunodeficiency status or selective depletion of activated CD4+ T cells." (PMID 39181733, 2024). "Moreover, I-TAC is a CXCR3-ligand that when elevated in the plasma has been shown to promote CD4 T-cell (FoxP3+) activation that was also associated with severe disease progression in HIV-1 infection." (PMID 37874153, 2023). "In addition, HIV-1 infection upregulates glycolysis to meet the demands of viral replication and CD4+ T-cells with higher glycolysis rate are more susceptible to HIV-1 infection." (PMID 38179408, 2023). "Furthermore, the low-level replication of the vaccine vector in vaccinated individuals would require replication in CD4+/CCR5+ cells (e.g., CD4+ T cells and macrophages), the same cell types susceptible to HIV-1 infection." (PMID 37243081, 2023). "Besides CD4+ T-cell depletion, HIV-1 infection also causes defective B-cell responses due to the loss of proper CD4+ T-cell responses." (PMID 36239345, 2023). "In agreement with this statement, treatment of CD4+ osteoblasts with the glucosylceramide synthase inhibitor 1-phenyl-2-hexadecanoylamino-3-morpholino-1-propanol (PPMP) has been shown to significantly alter the susceptibility of these cells to HIV-1 infection." (PMID 37511488, 2023). "Thus, we depicted the composition of CD4+ T cell subsets and clusters, and their association with viral reservoirs and clinical factors in the peripheral blood of individuals with chronic HIV-1 infection." (PMID 38124099, 2023). "In particular, studies elucidating the role of glycolysis and glucose uptake in HIV-1 infection illustrate that the host capacity for increased glucose transport could condition CD4+ T cell and macrophage susceptibility to HIV-1 infection." (PMID 36762762, 2023). "Here, we investigate whether IRF-5 also contributes to memory CD4+ T cell loss during HIV-1 infection." (PMID 37227774, 2023). "Despite the fact that HIV-1 infects antigen-presenting cells (APCs) to a lesser extent than T cells, a major pathogenic process in HIV-1 infection is the uptake of HIV-1 by APCs followed by transfer of virus to CD4+ T cells, leading to explosive levels of virus replication within T cells." (PMID 35215997, 2022). "In contrast to what is known about ECs, it is currently unknown whether the VNPs status will last indefinitely during HIV-1 infection or whether a proportion of VNPs will experience immunological progression in the form of loss of CD4+ homeostasis (LoH)." (PMID 34668779, 2022). "In addition, CD98high CD4+ T cells displayed hyper-permissiveness to HIV-1 infection and possessed distinct immune phenotypic profiles associated with Th17 and peripheral follicular T helper (pTFH) characteristics." (PMID 36214569, 2022). "Extensive loss of CD4+ T cells occurs in the GI tract shortly after HIV-1 infection." (PMID 35938870, 2022). "Similarly, the combined actions of HIV-1 proteins, Nef and Vpu, released post- HIV-1 infection, caused decreased cell-surface expression of CD4 on T cells, resulting in higher levels of infection." (PMID 34973144, 2022). "The top downregulated transcripts in cells from treated individuals were the transcription factor ZNF90; NHSL2, which has unknown function; and IL7R, which has been shown to play a role in CD4 T cell loss during HIV-1 infection." (PMID 36175869, 2022). "Overall, we confirmed that the susceptibility of CD98high CD4+ T cells for HIV-1 infection increased significantly whether single-cycle or wild-type viral infection was implemented." (PMID 36214569, 2022). "Vitamin D (VitD) has shown to decrease T cell activation, reducing susceptibility to HIV-1 infection of CD4+ T-cells in vitro; however, if VitD decreases viral transfer from DCs to CD4+ T-cells is unknown." (PMID 35802715, 2022). "The loss of immune cells, notably CD4+ T-cells, is the defining feature of HIV-1 infection." (PMID 36290665, 2022).
HIV-1 infection (continued). "While reports are varied on the susceptibility of EC CD4+ T cells to HIV-1 infection, ECs consistently maintain the balance of CD4+ T helper (Th) 17 cell and regulatory (Treg) subsets similar to that of HIV-1 uninfected individuals, while the ratio of Th17/Treg cells is lower in viremic subjects." (PMID 35572502, 2022). "For instance, knockout of previously known HIV-1 interactors Cyclin T1 (CCNT1), Peptidylprolyl isomerase A (CYPA) and Lens epithelium–derived growth factor (LEDGF) reduced susceptibility to HIV-1 infection of primary human CD4+ T cells to approximately 20 percent of wild-type T cells." (PMID 35892930, 2022). "Decreased IgA SHM is linked to systemic and mucosal CD4+ T cell loss during in HIV-1 infection." (PMID 35938870, 2022). "Human Immunodeficiency Virus type 1 (HIV-1) infection causes generalized immunodeficiency which is characterized by a profound depletion of CD4 T cells, impairment of B and T cells function, and systemic immune activation which persists during the chronic phase of the disease." (PMID 35287587, 2022). "Isolated CD4 T-cells were more susceptible to cell death after HIV-1 infection than Jurkat cells." (PMID 35163318, 2022). "Ex vivo, CD4+T cell immune activation was not induced upon JAKi treatment and significant reductions in the frequency of activation markers HLA-DR and CD25 was observed, a condition which has been linked to increased susceptibility of CD4+T cells to productive HIV-1 infection." (PMID 36131914, 2022). "For each participant, we investigated whether the measured cellular half-lives of each CD4+ T-cell subset were associated with HIV-1 infection frequencies." (PMID 34544282, 2021). "HIV-1 infection and replication is far more prevalent in the CD4+ T cells of the GI mucosa than in blood CD4+ T cells, leading to rapid and severe loss of GI CD4+ T cells following infection." (PMID 34618690, 2021). "Polymorphisms in the FAS and FASL genes suggested that the FAS-670 polymorphism might be associated with apoptosis of T CD4+ lymphocytes after HIV-1 infection." (PMID 34067165, 2021). "All CD4+ T-cells isolated from LVLs were susceptible to HIV-1 infection except one (AEM9650)." (PMID 34122382, 2021). "Indeed, CD4+ T cells with inhibited apoptotic signals and mitochondrial dysfunction have been reported to be more susceptible to HIV-1 infection." (PMID 34202658, 2021). "Similarly, the antigen specificity and function of CD73+ CD4+ T cells will be important in understanding the effect of their loss on the pathogenesis of HIV-1 infection." (PMID 33477692, 2021). "Cross-sectional studies have shown reduced gut microbiota diversity and compositional shifts from Bacteroides to Prevotella predominance after HIV-1 infection, which have been linked to lower CD4 + T-cell count, higher inflammation, and increased immune activation." (PMID 34248876, 2021). "Of note, the CD4+ T cell levels have been observed to return to normal within the blood but not within the gastrointestinal tract, which represents a major site of T cell depletion due to HIV-1-induced apoptosis, causing an overall reduction in CD4+ T cells during chronic HIV-1 infection." (PMID 34198973, 2021). "The susceptibility of CD4+ iNKT cells to HIV-1 infection raises the possibility that these cells may contribute to the viral reservoirs." (PMID 34753817, 2021). "Following these promising results in humanized mice, the first phase 1 human clinical trial with ZFN-CCR5 mutated CD4+ T cells was conducted, showing that these genetically modified CD4+ T cells were more resistant to HIV-1 infection and led to decrease viral loads during ART interruption." (PMID 33868262, 2021). "Overall, our findings support a model in which CD4+ iNKT cells may be more susceptible to HIV-1 infection than conventional CD4+ T cells during AHI." (PMID 34753817, 2021).